COPS3 (COP9 signalosome subunit 3)
Diseases named in the same sentence as COPS3 in open-access papers:
COPS3 is named in the same sentence as 28 diseases in open-access papers, as found by Europe PMC text mining. Sharing a sentence is not in itself a finding about the gene and the disease. The quoted sentences say what the papers report.
osteosarcoma (12 papers, 2012 to 2024). A usually aggressive malignant bone-forming mesenchymal neoplasm, predominantly affecting adolescents and young adults. "Our previous study indicated that osteosarcoma patients with overexpression of COPS3 had a higher risk of lung metastasis." (PMID 29970115, 2018). "Both in vitro and in vivo experiments demonstrated that COPS3 loss suppressed metastasis to the lung of osteosarcoma cells." (PMID 29970115, 2018). "COPS3 encodes a protein with kinase activity that phosphorylates regulators involved in signal transduction and has found to be a potential oncogene in osteosarcoma, multiple myeloma and lung cancer." (PMID 25148247, 2014). "To explore the underlying mechanism of COPS3 in the regulation of osteosarcoma metastasis, we searched the Human Protein Reference Database (HPRD) to find proteins that may interact with COPS3." (PMID 29970115, 2018). "Moreover, we found that COPS3 loss reduced the expression of Beclin1, through which COPS3 participates in regulating the migration of osteosarcoma cells." (PMID 29970115, 2018). "However, the underlying mechanism by which COPS3 promotes metastasis of osteosarcoma and its role in autophagy remain unknown." (PMID 29970115, 2018). "Knockdown of COPS3 significantly reduced lung metastasis of osteosarcoma cells in mouse models, downregulated MEK and ERK signaling, and inhibited EMT by 90 kDa ribosomal S6 kinase (RSK), reducing metastasis of osteosarcoma cells." (PMID 35903293, 2022). "Recently, a new oncogene, COPS3, was discovered and revealed to be involved in metastasis of osteosarcoma." (PMID 29970115, 2018). "Taken together, these data reveal a novel function of COPS3 in the regulation of autophagy and highlight the relationship between autophagy and metastasis in osteosarcoma cells." (PMID 29970115, 2018). "The expression of COPS3 was detected in primary osteosarcoma tissues and matching lung metastasis tissues by immunohistochemistry (IHC)." (PMID 29970115, 2018). "We found that knockdown of COPS3 significantly reduced the lung metastasis of osteosarcoma cells in a mouse model, coinciding with downregulation of mitogen-activated protein kinase (MEK) and extracellular signal-regulated kinase (ERK) signaling." (PMID 29970115, 2018). "The effect of COPS3 on the metastasis of osteosarcoma cells was investigated by transwell, wound healing assays and animal studies." (PMID 29970115, 2018). "COPS3 is located in chromosome region 17p11.2, which was demonstrated to be amplified in osteosarcoma by comparative genomic hybridization (CGH)." (PMID 29970115, 2018). "The results demonstrated that lung metastasis tissues had significantly higher IHC scores than those of primary osteosarcomas, suggesting that osteosarcoma cells with high expression of COPS3 are likely to metastasize." (PMID 29970115, 2018). "The gene list includes COPS3 in 17p11.2 and PMP22 in 17p12, which we and others previously suggested to act as causative oncogenes in osteosarcoma tumourigenesis." (PMID 22292074, 2012). "COP9 signalosome subunit 3 (COPS3) is an oncogene that promotes lung metastasis in osteosarcoma." (PMID 38699234, 2024). "COPS3 is an important oncogene involved in metastasis of osteosarcoma." (PMID 35903293, 2022).
osteosarcoma (continued). "Previous studies have revealed that COPS3 promotes osteosarcoma cell migration and invasion, and suppression of COPS3 could inhibit growth and induce apoptosis in lung cancer and hepatocellular carcinoma." (PMID 29970115, 2018). "COPS3 is a critical oncogene involved in the metastasis of osteosarcoma." (PMID 29970115, 2018). "Therefore, we reason that COPS3 might function in a cell type-dependent manner concerning its role in the growth of cancer cells, whereas it mainly acts to promote metastasis in osteosarcoma cells." (PMID 29970115, 2018). "However, it remains unknown whether the expression of COPS3 was different between primary osteosarcomas and matched lung metastasis tissues." (PMID 29970115, 2018). "In a recent study, further support for an oncogenic role for COPS3 was provided by demonstrating that RNAi-mediated COPS3 gene silencing inhibits the metastatic potential of osteosarcoma cells, suggesting that COPS3 overexpression might have an important role in the metastasis of osteosarcoma cells." (PMID 22292074, 2012). "For instance, COP9 signalosome subunit 3 (COPS3, LRT p value = 1.11 × 10−6) is closely associated with tumor development and knockdown of COPS3 significantly downregulated MEK signaling, reducing metastasis of osteosarcoma cells." (PMID 37395176, 2023). "COPS3 interacts with Raf-1 and activates MEK/ERK signaling to regulate osteosarcoma metastasis via autophagy." (PMID 37626810, 2023). "Of note, overexpression of genes belonging to the amplified region (COPS3, PMP22, GID4, ARGHAP44, TOP3A, SHMT1, and RASD1) was studied in osteosarcoma cell lines." (PMID 35920001, 2022). "A previous study also revealed that COPS3 played a vital role in linking Raf-1/MEK/ERK pathway and autophagic regulation in osteosarcoma." (PMID 35903293, 2022). "Expression of COP9 signalosome subunit 3 (COPS3), an oncogene overexpressed in osteosarcoma, has been demonstrated to be significantly correlated with tumor metastasis." (PMID 29970115, 2018). "While Raf-1 appeared in COPS3 immunoprecipitates, the antibody against Raf-1 was also able to pull down COPS3 in both 143B and HOS osteosarcoma cell lines, confirming direct binding between COPS3 and Raf-1." (PMID 29970115, 2018). "In an earlier small-scale study, we found genes COPS3 in 17p11.2 and PMP22 in 17p12 to be most consistently overexpressed after amplification in osteosarcomas, making these genes candidate oncogenes in that segment." (PMID 22292074, 2012). "We conclude that these genes, including COPS3 and PMP22, are candidate oncogenes in 17p11.2–p12 of importance in osteosarcoma tumourigenesis." (PMID 22292074, 2012). "Our previous study demonstrated that the frequency of COPS3 overexpression was significantly higher in osteosarcoma patients with metastasis than in patients without metastasis, and COPS3 silencing decreased the migration ability of osteosarcoma cells." (PMID 29970115, 2018). "However, prognostic studies for the other candidate genes require the development of new antibodies (C17orf39, RICH2, RASD1) or testing of available antibodies on osteosarcoma tissues (TOP3A, COPS3, SHMT1, PRPSAP2, PMP22), which is presently underway." (PMID 22292074, 2012). "Based on our statistical analysis of the correlation between copy number increase and expression level for each of the top ranking genes, we identified RICH2, c17orf45, TOP3A, COPS3, SHMT1, PRPSAP2, PMP22, and RASD1 as candidate osteosarcoma oncogenes in the 17p11.2-p12 region." (PMID 22292074, 2012). "Moreover, overexpression of COPS3 did not significantly enhance cell proliferation, although its overexpression markedly increased cell migration and invasion in osteosarcoma SAOS-2 cells." (PMID 29970115, 2018). "However, our data clearly show that COPS3 silencing did not significantly inhibit osteosarcoma growth in vivo." (PMID 29970115, 2018).
lung carcinoma (3 papers, 2014 to 2022). "The ablation of COPS3 suppressed the proliferation of lung cancer cells via induction of cell cycle arrest and stimulation of apoptosis." (PMID 35903293, 2022). "COPS3 depletion could inhibit the growth of lung cancer and liver cancer cells and induce apoptosis." (PMID 35903293, 2022).
clear cell renal cell carcinoma (2 papers, 2022 to 2024). "Alternatively, COPS3 may promote clear cell renal cell carcinoma progression by regulating phospho-AKT (Thr308), Cyclin D1, and Caspase-3 expression, while COPS5, -6, and -8 overexpression enhanced cellular proliferation, EMT, and vascular invasion." (PMID 38466642, 2024). "In addition, the overexpression of COPS3 could contribute to the progression of clear cell renal cell carcinoma (ccRCC) via regulation of phospho-AKT, Cyclin D1, and Caspase-3." (PMID 35903293, 2022).
colorectal cancer (2 papers, 2022 to 2024). A primary or metastatic malignant neoplasm that affects the colon or rectum. "COPS3 promotes the proliferation, invasion, and epithelial-to-mesenchymal transition of colorectal cancer cells through the MEK/ERK signaling pathway." (PMID 38699234, 2024). "However, there are few studies on the role of COPS3 in colorectal cancer, particularly colon adenocarcinoma (COAD)." (PMID 35903293, 2022). "This study investigated the effects of COPS3 on proliferation, motility, and EMT of colorectal cancer cells and related mechanisms." (PMID 35903293, 2022). "This study investigated the effects of COPS3 on proliferation, migration, invasion, and EMT of colorectal cancer cells and related mechanisms." (PMID 35903293, 2022).
COVID-19 (2 papers, 2024 to 2025). A disease caused by infection with severe acute respiratory syndrome coronavirus 2. "Four upregulated common genes (DHX15, USP14, COPS3, TYK2) and one downregulated common feature gene (RIOK2) were identified and showed good diagnostic accuracy for T2DM and COVID-19." (PMID 38699234, 2024). "We constructed a PPI network and identified five common feature genes (DHX15, USP14, COPS3, TYK2, and RIOK) of T2DM and COVID-19 by extracting the core genes of the network." (PMID 38699234, 2024). "Thus, COPS3 may regulate the development of COVID-19 by modulating autophagy." (PMID 38699234, 2024). "We identified five common feature genes between T2DM and COVID-19: DHX15, USP14, COPS3, TYK2, and RIOK2 (where DHX15, USP14, COPS3, and TYK2 were upregulated and RIOK2 was downregulated)." (PMID 38699234, 2024). "The roles of DHX15, USP14, COPS3, TYK2, and RIOK2 in T2DM and COVID-19 remain primarily unknown, emphasizing the importance of future research." (PMID 38699234, 2024). "The results from the ROC curve analysis showed that DHX15, USP14, COPS3, TYK2, and RIOK had AUC values of 0.931, 0.917, 0.986, 0.903, and 0.917, respectively, for T2DM and AUC values of 0.960, 0.860, 1.0, 0.9, and 0.90, respectively, for COVID-19." (PMID 38699234, 2024). "We identified five common feature genes (DHX15, USP14, COPS3, TYK2, and RIOK2) and their co-regulatory pathways between T2DM and COVID-19, which may provide new insights for molecular mechanism studies." (PMID 38699234, 2024). "In the validation dataset, the AUC values of DHX15, USP14, COPS3, TYK2, and RIOK were 0.922, 0.781, 0.812, 0.844, and 0.984, respectively, for T2DM, and 0.733, 0.687, 0.737, 0.782, and 0.632, respectively, for COVID-19." (PMID 38699234, 2024). "We identified five common feature genes (DHX15, USP14, COPS3, TYK2, and RIOK2) and their co-regulatory pathways between T2DM and COVID-19, which may provide new insights for further molecular mechanism studies." (PMID 38699234, 2024).
multiple myeloma (2 papers, 2012 to 2014). "Overexpression of SHMT1 and PRPSAP2 (and also COPS3) has been reported to occur in multiple myelomas." (PMID 22292074, 2012).
allergies (1 paper, 2017). "Additionally, Cops3 has been implicated in keratinocyte interleukin signaling, which is interesting in light of the recent observation that loss of Dsg1 leads to an increase in inflammatory mediators in SAM syndrome, featuring severe dermatitis, multiple allergies, and metabolic wasting." (PMID 28891468, 2017).
colon adenocarcinoma (1 paper, 2022). "However, there are few studies on the role of COPS3 in colon adenocarcinoma (COAD)." (PMID 35903293, 2022).
glioma (1 paper, 2021). A benign or malignant brain and spinal cord tumor that arises from glial cells (astrocytes, oligodendrocytes, ependymal cells). "Notable genes with SNV-associated increased expression include TERT, COPS3, POLE2 and HDAC2—involving multiple cancer types—MYC, BCL2, PIM1 and IGLL5—involving lymphomas—and CYHR1—involving pediatric low-grade gliomas." (PMID 33554123, 2021).
leiomyosarcoma (1 paper, 2017). An uncommon, aggressive malignant smooth muscle neoplasm, usually occurring in post-menopausal women. "The pattern of 17p loss in conjunction with COPS3 amplification was present in a group of 267 soft tissue sarcomas, particularly in leiomyosarcoma." (PMID 28643781, 2017).
lung adenocarcinoma (1 paper, 2024). A carcinoma that arises from the lung and is characterized by the presence of malignant glandular epithelial cells.
oropharyngeal carcinoma (1 paper, 2023). Carcinoma, predominantly squamous cell, arising from the epithelial cells of the oropharynx. "High levels of the COPS3 protein have been reported in different cancers, including oral and oropharyngeal carcinoma." (PMID 37174723, 2023).
prostate carcinoma (1 paper, 2022). A carcinoma that arises from epithelial cells of the prostate gland. "Depletion of COPS3 could suppress the progression of prostate cancer through reducing phosphorylated p38 MAPK and impairs the EMT." (PMID 35903293, 2022).
sarcoma (1 paper, 2024). A usually aggressive malignant neoplasm of the soft tissue or bone. "Similarly, fusions involving driver genes largely or exclusively restricted to sarcoma (e.g. KMT2A::YAP1 in case 9) are readily detectable, as are the more sarcoma-specific copy number targets (e.g. COPS3 in case 17 and MYOCD in case 13)." (PMID 38997407, 2024).
cancer (8 papers, 2017 to 2026). A tumor composed of atypical neoplastic, often pleomorphic cells that invade other tissues. "(e) A 32 kDa S-tagged C-terminal truncation of Dp (DP-S-tag) associates with Cops3 in squamous cell carcinoma line 9 (SCC9) lysates." (PMID 28891468, 2017). "This study focuses on the key gene COPS3 in this region, delving into its molecular mechanisms regulating cancer stemness." (PMID 41824786, 2026). "Based on these findings, we identified Z-5891, a highly selective COPS3 inhibitor that suppresses tumor growth and reduces cancer stemness in vitro and in vivo." (PMID 41824786, 2026). "GEPIA2 database analysis of 33 cancer types showed the following top 10 ALKBH5-related genes: GID4 (R=0.71), TOP3A (R=0.67), MAPK7 (R=0.66), NT5M (R=0.61), FLII (R=0.59), ZNF18 (R=0.57), DRG2 (R=0.57), COPS3 (R=0.56), MED9 (R=0.56) and PRPSAP2 (R=0.56) (all P<0.0001)." (PMID 35444654, 2022).
tumor (8 papers, 2012 to 2026). "Previous research had shown that the amplification of COPS3 was strongly associated with a large tumor size (P = 0.0009)." (PMID 32318090, 2020). "While high levels of COPS3, DYHC1, and S100A8 were unfavorable for tumor recurrence, low amounts of A2M and Serpine 1 were associated with better DFS." (PMID 37174723, 2023). "We noticed that the transcript per million of COPS3 in primary tumor tissues (n = 286) was higher than normal (n = 41), suggesting the high expression in COAD." (PMID 35903293, 2022). "MMP-9, a member of the matrix metalloproteinase family and a critical player in tumor invasion, expression was also decreased in COPS3-depleted 143B and HOS cells." (PMID 29970115, 2018). "In addition, COPS3 depletion inhibited tumor growth in nude mice by blocking cell cycle progression." (PMID 35903293, 2022). "Among them, COPS3, DYHC1, and S100A8 are unfavorable for tumor recurrence and survival, in contrast to A2M and Serpine1, low levels of which show an association with better DFS." (PMID 37174723, 2023). "The previous study indicated the effects of COPS3 on the MEK/ERK pathway, which could mediate the proliferation, motility, and EMT in several types of tumor cells." (PMID 35903293, 2022).
infection (1 paper, 2018). The state of being infected such as from the introduction of a foreign agent such as serum, vaccine, antigenic substance or organism. "Stable knockdown of COPS3 in 143B and HOS cell lines was established via lentivirus-mediated silencing, while overexpression of COPS3 was accomplished by adenovirus-mediated infection in the SAOS-2 cell line, which has relatively low expression of COPS3." (PMID 29970115, 2018).
COPS3 also shares sentences with these, for which no sentence is quoted: potassium deficiency (2 papers); acute myeloid leukemia (1); autism (1); dermatitis (1); diabetes (1); hepatocellular carcinoma (1); liver cancer (1); lymphoma (1); myelodysplastic syndrome (1); Smith-Magenis syndrome (1); soft tissue sarcoma (1).